FGF19 (fibroblast growth factor 19)
Diseases named in the same sentence as FGF19 in open-access papers (continued):
Sharing a sentence is not in itself a finding about the gene and the disease.
Obesity (continued). "Additionally, in order to obtain information on the metabolic benefits of FGF19 and FGF19-7 in an adult on-set model of obesity, B6D2F1/J male mice were first put on high fat diet at 3–4 weeks old prior to AAV virus injection." (PMID 22457778, 2012). "Moreover, the upregulation of the thermogenesis pathway observed in our study could be attributed to the capability of FGF19 to induce an anti-obesity effect on adipose tissue, via stimulation of white adipose tissue browning." (PMID 40211057, 2025). "Furthermore, they also showed that FGF19 was able to protect the skeletal muscle against obesity-induced muscle atrophy through the AMP-activated protein kinase (AMPK)-Sirtuin-1 (SIRT1)-PGC1α pathway, which may be a potential target for obesity treatment." (PMID 34572066, 2021). "Taken together, this study suggests that FGF19 protects skeletal muscle against obesity‐induced muscle atrophy, metabolic derangement and abnormal irisin secretion partially through the AMPK/SIRT‐1/PGC‐α signalling pathway, which might be a potential therapeutic target for obesity and SO." (PMID 33751819, 2021). "Further definitions of the BA/FXR/FGF19/FGFR4 axis phenotypes, and their relevance to disease, whether primary, caused by genetic polymorphisms, or secondary to acquired factors such as obesity or metformin, is an area of on-going research, both in BAD and in NAFLD and NASH." (PMID 30682184, 2019). "A statistically significant difference was also found between the concentrations of FGF-19 and FGF-22 (p = 0.001; p < 0.001) in the serum of people with normal weight and people with overweight and obesity." (PMID 40943671, 2025). "Serum concentrations of FGF-19 and FGF-21 were measured in 137 individuals with obesity and different degrees of insulin resistance matched by sex, age, and body adiposity and compared to 33 lean individuals." (PMID 41155711, 2025). "In contrast to FGF19, plasma FGF21 concentrations were elevated in patients with severe obesity, especially in those with diabetes, and were strongly associated with liver damage." (PMID 40943431, 2025). "In particular, promising data revealed that fibroblast growth factor (FGF)-19, FGF-21 and leptin offer great potential for future clinical application in the treatment of obesity and related comorbidities." (PMID 37239098, 2023). "In addition, AMP-activated protein kinase/sirtuin 1 (AMPK/SIRT1), fibroblast growth factor-19/21 (FGF19/21), Janus kinase/signal transducer and activator of transcription (JAK/STAT), and Notch signaling pathways implicated in obesity could also be investigated." (PMID 35215280, 2022). "In conclusion, we confirmed serum FGF-19 and FGF-21 as useful new markers of obesity-related metabolic alternations and we robustly propose Rb as a novel indicator of excessive body adiposity and its early consequences." (PMID 36362225, 2022). "Although some animal studies have suggested the therapeutic potential of FGF-19 and FGF-21 in the treatment of obesity, diabetes or metabolic syndrome, still little is known about their role in the metabolic disorders." (PMID 36362225, 2022). "Therefore, FGF19 might become a therapeutic target for improving obesity and SO." (PMID 33751819, 2021). "The discovery of the FGFs (FGF19, FGF21) and their influences on the body energy balance as hormones demonstrate significant progress in obesity and type 2 diabetes studies." (PMID 31151464, 2019). "The endocrines FGF19, FGF21, and FGF23, have great potential to be important therapeutics for a variety of human diseases such as obesity, type II diabetes, and kidney and cardiovascular diseases." (PMID 30068552, 2018). "Fibroblast growth factor (FGF)-19, an endocrine FGF protein mainly produced by the ileum, stimulates metabolic activity and alleviates obesity." (PMID 24176017, 2013). "Several studies have now demonstrated that administration of FGF19 or FGF21 can have beneficial effects in rodent and primate models of obesity and diabetes." (PMID 22675463, 2012).
Obesity (continued). "Both FGF19 and FGF21 transgenic mice are resistant to diet-induced obesity, have decreased adiposity and improved insulin sensitivity, glucose disposal, and plasma lipid profiles." (PMID 22457778, 2012). "Recent studies suggest that betaKlotho (KLB) and endocrine FGF19 and FGF21 redirect FGFR signaling to regulation of metabolic homeostasis and suppression of obesity and diabetes." (PMID 22442730, 2012). "Key organokines such as fibroblast growth factors FGF19 and FGF21, adiponectin, galectin-3, irisin, and leptin represent well-characterized mediators of inter-organ communication with direct implications in obesity-related metabolic dysfunction." (PMID 40943431, 2025). "Altered MABA profiles correlate with T2D, obesity and inflammatory bowel disease; experimental data indicate improved glucose homeostasis and reduced adiposity with specific MABAs; potential to modulate gut–brain signaling via GLP-1 and FGF19." (PMID 41465592, 2025). "In our study, elevated CK-18 plasma levels were accompanied by elevated FGF-21 levels in obesity, whereas FGF-19 was not related." (PMID 37189422, 2023). "Accumulating evidence reveals that obesity accelerates the secretion of hepatokines from hepatocytes such as hepassocin (HPS), angiopoietin-like protein 8 (ANGPTL8), Fetuin-A and B and fibroblast growth factor 19 and 21 (FGF19/21)." (PMID 37361533, 2023). "Activation of intestinal FXR promotes the secretion of FGF19, which could be exploited therapeutically as patients with obesity and T2DM have lower FGF19 levels." (PMID 37560311, 2023). "A recent meta-analysis demonstrated a negative association between FGF 19 levels and the degree of BMI reduction after bariatric surgery, while obesity and DM led to significantly lower FGF 19 levels compared to those without DM." (PMID 35277004, 2022). "The endocrine subfamily of FGFs, consisting of FGF19, FGF21, and FGF23, might have beneficial effects in the treatment of diabetes mellitus (DM) and/or obesity." (PMID 36699319, 2022). "Our study supports the notion that both FGF 19 and 21 may have complementary advantages in evaluating these two major comorbidities, T2DM and NAFLD, of obesity, respectively." (PMID 35277004, 2022). "Further, patients with obesity and DM have significantly lower FGF 19 levels than patients with obesity but without DM." (PMID 31181641, 2019). "In mice with obesity genetically induced by ablation of brown adipose tissue or lack of leptin, FGF19 prevented or reversed diabetes." (PMID 30927227, 2019). "FGF 19 transgenic mice did not develop obesity and DM on a high-fat diet by reducing fat mass, increasing energy expenditure, increasing insulin sensitivity, and reducing hepatosteatosis." (PMID 31181641, 2019). "The observed alterations in FGF-2, FGF-19, FGF-22, and FGF-23 concentrations—particularly their associations with hypertension, obesity, nephropathy, and joint degeneration—support their role not only in the pathogenesis but also in the clinical stratification of diabetic complications." (PMID 40943671, 2025). "Furthermore, the study highlights that reduced levels of FGF-19 and FGF-22 in individuals suffering from obesity may reflect a more profound link between these growth factors and excess body weight." (PMID 40943671, 2025). "In this study, we analysed the postprandial responses of bile acids, C4 and FGF19 in plasma, and excretion of bile acids in faeces, before and after bariatric surgery in patients (n = 38; 74% females) with obesity with or without type 2 diabetes from the BARIA cohort." (PMID 39096744, 2024). "However, juvenile Iberian pigs with NAFLD had decreased FGF19 expression in the absence of obesity and IR, suggesting that FXR dysregulation cannot be attributed solely to underlying metabolic conditions." (PMID 38137523, 2023).
Obesity (continued). "Recently, the new proteins of the same family members, fibroblast growth factor-19 (FGF-19) and fibroblast growth factor-21 (FGF-21), with pleiotropic effects on development, organogenesis and metabolism have been proposed to be involved in the pathogenesis of obesity." (PMID 36362225, 2022). "It is suggested that although FGF-19 and FGF-21 are activated under different conditions, they show a similar function in their controlling of glucose and insulin metabolism, energy and weight balance as well as lipid concentrations, particularly in metabolic disorders such as obesity or diabetes." (PMID 36362225, 2022). "However, the protective effects of FGF19 on skeletal muscle in obesity and SO are still not completely understood." (PMID 33751819, 2021). "This feedback regulation of FGF 19 in human hepatic bile acid synthesis supports our new findings, which revealed decreasing bile acid levels 1 year after SG in the patients with obesity and T2DM, and the negative relationship between FGF 19 and total bile acid." (PMID 31181641, 2019). "The negative correlation between FGF19 and obesity has also been confirmed in animal studies." (PMID 30927227, 2019). "For this purpose, in rats with obesity induced by a high-calorie diet (HCD), we determined the serum concentration of the two new hormones—FGF-19 and FGF-21—whose role in the pathogenesis of obesity is suggested, but not yet established." (PMID 36362225, 2022). "For this purpose we determined serum FGF-19 and FGF-21 concentrations in obese rats, whose role in the pathogenesis of obesity is not yet established." (PMID 36362225, 2022). "Not much is known about these cytokines in relation to obesity or HDL, apart from for FGF19 which, like its related hormone FGF21 mentioned earlier, is being investigated as a pharmacological target for obesity." (PMID 33204460, 2020). "Lean NAFLD is a special obesity resistant classification of NAFLD and believed to be with a distinct pathophysiological feature, characterized by higher serum secondary bile acid, increased expression of FGF19 and a shifted gut microbiota profile compared with non-lean NAFLD." (PMID 35662732, 2022).
diabetes (54 papers, 2011 to 2026). "Ln-transformed FGF19 levels were also negatively associated with diabetes after adjusting for covariates, including age, sex, smoking status, alcohol consumption, blood pressure, BMI, waist circumference, and lipid profile [OR (95% CI): 0.66 (0.47–0.95)]." (PMID 41522208, 2026). "Serum FGF19 levels are inversely associated with diabetes risk in the Chinese population, with BMI serving as a partial mediator of this relationship." (PMID 41522208, 2026). "Our study not only demonstrated the association between FGF19 and diabetes but also utilized a mediation analysis that allowed us to fully investigate the relationships between FGF19, BMI, and diabetes." (PMID 41522208, 2026). "Apart from diabetes, serum FGF19 level was also negatively associated with diabetes-related complications, such as diabetic retinopathy, diabetic nephropathies, subclinical atherosclerosis and polycystic ovary syndrome." (PMID 41522208, 2026). "Alterations in the bile acid pool and signaling tone represent a plausible medium-sized pathway between circulating FGF19 and diabetes risk." (PMID 41522208, 2026). "The strength of this study lies in its large sample size and the use of mediation analysis to elucidate the underlying mechanisms of the relationship between FGF19 and diabetes." (PMID 41522208, 2026). "Mediation analysis revealed that BMI reduction accounted for 10.1% of the association between ln-transformed FGF19 levels and diabetes." (PMID 41522208, 2026). "The association between ln-transformed FGF19 levels and diabetes was partially mediated by BMI, with the proportion of 10.1% (P-value < 0.05)." (PMID 41522208, 2026). "Specifically, serum FGF19 levels negatively associated with odds of diabetes, and this relationship is about 10% mediated by the reduction of BMI." (PMID 41522208, 2026). "Mediation analysis was conducted to assess the extent to which BMI mediated the association between serum FGF19 levels and diabetes." (PMID 41522208, 2026). "Elevated insulin resistance, non-alcoholic fatty liver disease, and diabetes mellitus were linked to altered plasma FGF19 levels." (PMID 39950129, 2025). "Prior research has identified FGF19 as a potential target for managing diabetes and its associated complications." (PMID 39040677, 2024). "The administration of recombinant human FGF19 or FGF19 overexpression in leptin deficient diabetic mice was shown to reduce weight gain, reverse diabetes, increase lipid oxidation rate decreasing also hepatic triacylglycerol content." (PMID 30559664, 2018). "The diagnosis of diabetes and liver fibrosis were associated with lower FGF19 levels, while, higher FGF21 levels were associated with hypertension." (PMID 25664662, 2015). "Transgenic expression of the human FGF19 gene in obese/diabetic mice was shown to cause an increase in energy expenditure and reversed hepatic steatosis, hyperlipidemia, and diabetes." (PMID 24130687, 2013). "The partial mediation of this relationship by BMI reduction suggests that weight management may be an important strategy for improving FGF19 levels and reducing diabetes risk." (PMID 41522208, 2026). "For example, FGF19 exhibited improved mitochondrial efficiency, which might be associated with higher cardiac contractility in hearts of patients with diabetes." (PMID 37186335, 2023). "To explore the in vivo role of FGF19 in cholesterol homeostasis in the context of diabetes, a global health concern that is frequently associated with dyslipidemia, we introduced and expressed FGF19 transgenes in diabetic db/db mice by intravenous AAV delivery methods." (PMID 30679232, 2019). "In addition, direct administration of recombinant FGF-15 (FGF-19 in humans) to obese mice leads to significant weight reduction, principally AT reduction, and reverses dietary and leptin-deficient diabetes." (PMID 28202005, 2017).
diabetes (continued). "Third, we did not distinguish between different types of diabetes (e.g., type 1 diabetes, type 2 diabetes, or other specific forms), and the association between FGF19 and diabetes may differ by diabetes subtype; future studies with detailed phenotyping and subtype classification are warranted." (PMID 41522208, 2026). "Therefore, part of the observed inverse association between FGF19 and diabetes may reflect downstream effects on bile acid composition and receptor-mediated metabolic signaling, which were not directly measured in our dataset." (PMID 41522208, 2026). "FGF19 has been shown to be inversely associated with body mass index, metabolic syndrome and Type 2 diabetes mellitus (DM) and levels increase following bariatric surgery." (PMID 39341924, 2024). "In addition, we show that FGF19 mRNA was stimulated by meal replacement drinks (Ensure, Glucerna, SlimFast), non-fat milk, and coffee which has been linked with reduced risk for developing diabetes." (PMID 24465600, 2014). "The mechanism linking FGF19, BMI, and diabetes is a complex interplay involving various biological processes." (PMID 41522208, 2026). "In contrast, statistically significant differences in median FGF-19 concentrations were observed among individuals with different BMI values (p = 0.038 in the overall cohort; p = 0.001 in patients with diabetes)." (PMID 40943671, 2025). "Exogenous supplementation with recombinant FGF19 protected ob/ob mice from diabetes and improved glucose metabolism." (PMID 41114583, 2025). "FGF19 can lower plasma glucose levels and lower body weight, as well as preventing the development of diabetes." (PMID 36927328, 2023). "The same group later reported that administration of FGF19 to obese mice resulted in increased metabolic rate, decreased respiratory quotient, and prevention or reversal of diabetes." (PMID 35116006, 2021). "In conclusion, we have demonstrated that high circulating FGF19 levels predicted the development of subclinical atherosclerosis in men with type 2 diabetes in this Chinese diabetes cohort." (PMID 32528406, 2020). "FGF19 also stimulates glycogen synthesis in mice with streptozotocin-induced diabetes with very low insulin levels." (PMID 30927227, 2019). "After the surgery, a gradual increase in FGF19 and fatty acids concentrations was observed in all patients; however, it was greater in people with diabetes." (PMID 30927227, 2019). "The reason for this discrepancy in the serum levels of FGF19 in subjects with diabetes is unclear and requires exploration through further studies." (PMID 31572498, 2019). "FGF19 has been widely discussed and has potential as a therapeutic target for metabolic disorders, including diabetes." (PMID 31572498, 2019). "The beneficial impact of FGF19 on lipid, glucose and BA homeostasis raise the possibility to pursue FGF19 as a therapeutic target for diabetes, metabolic syndrome and cholestatic liver diseases." (PMID 28178326, 2017). "Changes in circulating FGF-19 levels were surgery-specific, with BPD producing the best metabolic outcomes among the study procedures (BPD > LGCP > LAGB), and highlighting mitochondria in AT as a potential target of FGF-19 during diabetes remission." (PMID 28202005, 2017). "FGF19 serum levels are significantly lower in Class III obese patients with diabetes as well as in typical diabetic patients with mean BMI of 30 kg/m2." (PMID 25664662, 2015). "Subsets of No-T2D and T2D patients were randomly selected and further divided according to their RYGB postoperative diabetes remission status for the measurements of the FGF19/21 serum levels." (PMID 25664662, 2015). "Serum FGF19 levels are decreased in patients with type 2 diabetes, indicating that the FGF19 pathway is significantly perturbed in severe diabetes." (PMID 26483756, 2015). "We recently showed that FGF19 levels were lower and bile acids higher in patients with type 2 diabetes (referred to herein as “T2D” or “diabetes”)." (PMID 24465600, 2014).